INS (insulin)
Diseases named in the same sentence as INS in open-access papers (continued):
Sharing a sentence is not in itself a finding about the gene and the disease.
prediabetes (continued). "We hypothesized that exercise training would increase insulin-stimulated GU and decrease fasting FFAU in subjects with T2DM or prediabetes, and that SIT would be more effective to induce these adaptations compared to MICT." (PMID 28874821, 2017). "When looking at the insulin sensitivity indexes, we observed higher HOMA-IR in prediabetes and T2D." (PMID 28986547, 2017). "Therefore, unlike the descriptions from previous studies that prediabetic subjects have decreasing insulin secretory responses, the HFHF pigs showed excessive secretion of insulin by IVGTT during the early stage of prediabetes." (PMID 29046729, 2017). "The major finding from the present study is that a single high intensity exercise bout lowers GSIS relative to hepatic and adipose tissue insulin resistance when compared to an isocaloric matched moderate bout in adults with prediabetes independent of sex." (PMID 27111219, 2016). "Previous studies have demonstrated an increased proinflammatory state among individuals with prediabetes who are predominantly insulin resistant, but not among those with primary defects in β-cell function and insulin secretion." (PMID 26458065, 2015). "Since GLP-1 is an insulin secretagogue and a suppressor of glucagon secretion, defects in GLP-1 secretion could contribute to the pathogenesis of prediabetes." (PMID 26075286, 2015). "Skeletal muscle gene expression of PPARGC1A and genes involved in oxidative phosphorylation has been extensively studied in relation to prediabetes and T2D, and increased skeletal muscle expression of PPARGC1A is believed to contribute to improved insulin sensitivity." (PMID 23505498, 2013). "For these reasons, a chronic high protein diet may not be suitable for those with T2D or prediabetes, as excess amino acids can desensitize tissue to insulin and contribute to other organ complications." (PMID 41602572, 2026). "However, to date, no studies have examined whether exercise may impact nEV cargo as it relates to insulin signaling mediators and pro‐BDNF in older adults with prediabetes." (PMID 39421964, 2025). "Moreover, a 12-week blueberry supplementation study in individuals with prediabetes and subjective cognitive decline reported lower fasting insulin levels, although no significant changes were observed in fasting blood glucose or HOMA-IR scores." (PMID 40430501, 2025). "The overlap of several pathways, such as insulin, NOTCH, and PI3K-Akt signaling, across the prediabetes and T2D groups could indicate that these pathways play a fundamental role in the metabolic dysregulation observed in both groups with impaired glucose metabolism." (PMID 41373473, 2025). "However, the impact of intermittent fasting on glucose regulation in individuals with prediabetes remains poorly understood, and its long-term role in the insulin signalling pathway is not yet well-defined." (PMID 39861423, 2025). "Although ILC subsets at Visit 1 could not predict the progression from GDM to prediabetes, ILC2 frequency was associated with insulin sensitivity index (ISI), whereas percent HLA-DR+ ILC1s were inversely correlated." (PMID 40129978, 2025). "However, other studies found no significant improvements in insulin sensitivity after intervention periods of 6 and 24 weeks among individuals with prediabetes." (PMID 40430501, 2025). "Consistently, here, we found that 30.3% of women with a history of GDM without insulin treatment during pregnancy and 42.8% of GDM patients with insulin treatment during pregnancy as opposed to 17.8% of women with normoglycemic pregnancies had developed prediabetes at the 5-year follow-up (Visit 2)." (PMID 40129978, 2025). "Conversely, as compared with women with NGT, only women with T2DM exhibited a significant (P = 0.02) age-adjusted lower whole-body insulin-stimulated glucose disposal value, whereas those with prediabetes exhibited a numerically lower mean value, although not statistically significant." (PMID 38671460, 2024).
prediabetes (continued). "This study aimed toinvestigate the serum levels of adiponectin and peroxisomeproliferator-activated receptors-gamma parameters, which are closely relatedto adipose tissue, energy metabolism, and insulin sensitivity, in obesepatients with and without prediabetes." (PMID 38655997, 2024). "Subjects with prediabetes generally have a lower insulin sensitivity but are not yet hyperglycemic." (PMID 39108361, 2024). "Therefore, higher insulin action in pediatric IFG, compared to other forms of prediabetes, may additionally explain the relatively lower glucagon levels placing them in the range of NG-O." (PMID 39027470, 2024). "β-cell dysfunction and decreased insulin secretion therefore may not appear until the later stages of prediabetes." (PMID 37571297, 2023). "First, this is retrospective data and hence other potential variables that could influence the prediabetes status such as gestational weight gain and insulin treatment were not electronically available." (PMID 37767000, 2023). "This negative correlation between Mg intake and prediabetes is biologically viable and can be explained in part by the fact that Mg plays an important role in glucose and insulin metabolism, mainly through the effect of tyrosine kinase activity, which transfers phosphate from ATP to protein." (PMID 36364842, 2022). "When these analyses were restricted to normoglycemic pGDM women and normoglycemic non-GDM women (i.e., women without T2DM or prediabetes), all estimates of insulin sensitivity, beta cell function, and compensatory beta cell function were similar in the two groups." (PMID 35789592, 2022). "Similarly, despite no national or international recommendations, insulin tests were requested by GPs, albeit infrequently and mostly for prediabetes management." (PMID 36411411, 2022). "The improvement in the TyG index and to a lesser extend the HOMA-IR is to be expected as the FPG levels improved significantly following linagliptin intervention in the high GLP-1 group of both the prediabetes and T2D populations despite the non-significant drop in the fasting insulin levels." (PMID 36267570, 2022). "Clinically, IFG and IGT are both considered signs of prediabetes but they are not always observed together, as they represent different homeostatic processes, with IFG associated with hepatic insulin insensitivity and IGT associated with peripheral insulin insensitivity." (PMID 35102183, 2022). "The increase of the endogenous opioids and their receptors in the prediabetes subgroups compared with the controls suggests the dependence of these parameters on the state of the glucose metabolism rather than its dependence on the insulin hormone response." (PMID 34099024, 2021). "Thus, the HFD mice secrete sufficiently elevated insulin to maintain a normal glucose level, and as such the HFD model may be better characterized as a prediabetes model." (PMID 32085589, 2020). "The major new finding in this study in obese and non-obese subjects with prediabetes or normal glucose tolerance was a highly significant and clinically relevant acute reduction in postprandial insulin and C-peptide responses on a diet reduced in carbohydrate and increased in protein and fat." (PMID 30213037, 2018). "However, increase in serum albumin concentrations was protective against prediabetes development, regardless of baseline BMI, BMI change, or insulin resistant status." (PMID 28430803, 2017). "However, as in the case of a previous study, this study’s results did not confirm this; the associations between glucose, fructose, and sucrose with BCF, insulin sensitivity, prediabetes, and T2DM were independent of total energy intake and WHR." (PMID 28406435, 2017). "The correlation of circulating miRNA abundance levels to measures of glycemic control, insulin secretion, and insulin action was examined for each individual group in the subset of subjects not on exogenous insulin (i. e., healthy controls, prediabetes, and T2D)." (PMID 27558530, 2016).
prediabetes (continued). "However, in a post hoc analysis restricted to participants with prediabetes (48% of the participants), there was a significant beneficial effect of vitamin D and calcium supplementation on insulin sensitivity, but not on insulin secretion or β-cell function." (PMID 25299668, 2014). "Finally, although all laboratory analyses were performed using standardized assays, dynamic tests of insulin sensitivity and secretion were not included, which might have provided a more comprehensive assessment of insulin physiology in women with prediabetes." (PMID 41384021, 2025). "Thus, the absolute level of insulin secretion may not consistently predict dysglycemia, especially in those with prediabetes, which constituted the majority of our dysglycemic group." (PMID 34206745, 2021). "For instance, proteins derived from milk are common interventions for prediabetes since significant improvements have been observed in oxidative stress markers and glucose metabolism, especially postprandial glucose and glycated hemoglobin A1c (HbA1c), without any improvements of insulin profiles." (PMID 33322540, 2020). "Thus, our findings suggest for the first time that fitness-related insulin sensitivity may modulate EV responses to an oral glucose load in obese adults with or without prediabetes." (PMID 30857250, 2019). "However, whether acute exercise at a relatively low dose (i.e. 200-kcal) of different intensities modifies the insulin secretion response in people with prediabetes is not presently clear." (PMID 27111219, 2016). "Insulin is currently the primary treatment modality for CFRD and possibly prediabetes; however, CFRD is a heterogeneous disease, and not all patients with CFRD need insulin therapy." (PMID 38541202, 2024). "In contrast to the high GLP-1 group, DPP-IV inhibition did not significantly alter plasma glucose, insulin levels, insulin resistance and beta cell function indices in the low GLP-1 prediabetes group." (PMID 36267570, 2022). "Of course, many of the mechanisms underlying GDM are not unique to GDM, encompassing other common disorders of insulin sensitivity, such as T2DM, prediabetes, and PCOS." (PMID 30373146, 2018). "Compared to those who showed no progression, subjects who progressed to prediabetes or T2DM consisted of more men (P = 0.019), were older, had greater BMI, WC, FPG and 2 hrG levels during OGTT, fasting insulin (all p<0.001) and HOMA-IR (P = 0.002)." (PMID 22163043, 2011). "The evidence gathered in this study showed that M. charantia in individuals living with prediabetes and T2D may significantly reduce FBG, HbA1c, insulin and HOMA-IR levels without affecting HOMA-β." (PMID 41280283, 2025). "Similarly, insulin levels also increased in those who had an inadequate abdominal WC, were overweight, had prediabetes, and had T2DM without insulin use." (PMID 36468927, 2023). "In addition, their fasting glucose and HbA1c in early pregnancy and fasting glucose, fasting insulin and HOMA2-IR in late pregnancy were higher than those of the women with no prediabetes." (PMID 36961590, 2023). "This phenomenon could be explained by GLP-1 resistance in prediabetes, in which GLP-1 fails to stimulate insulin production, increasing 2-hour postprandial blood glucose levels." (PMID 35075363, 2022). "The primary results of the POP-ABC study, which showed no ethnic disparity in the incidence of prediabetes among people with similar parental history of T2DM, identified baseline weight, insulin sensitivity, insulin secretion and inflammatory markers as significant associations of prediabetes risk." (PMID 36686435, 2022). "In the context of prediabetes and established T2DM, analyses from large-scale clinical trials (ORIGIN and DEVOTE) of cardiovascular events in recent years revealed that the use of insulin did not lead to major cardiovascular outcomes or to increased HF hospitalization and HF recurrence." (PMID 37542280, 2023).
prediabetes (continued). "Although neither of the two antidiabetic drugs used as prediabetes treatment, metformin and liraglutide, were able to reverse HFHSD-induced DM2, metformin was the superior intervention over liraglutide due to improved central leptin sensitivity and peripheral insulin sensitivity in females." (PMID 37929025, 2023). "The projected cost of metformin treatment for seven patients with prediabetes can avoid the cost of treating a non-complicated diabetic patient with metformin + glimepiride after 2.9 years; with metformin + DPP4 inhibitors after 2.6 years; and with metformin + insulin after 1.9 years." (PMID 31410086, 2017).
atherosclerosis (898 papers, 2002 to 2026). A disease characterized by the build-up of fatty material and calcium deposition in the arterial wall resulting in partial or complete occlusion of the arterial lumen. "HIIT also improves insulin sensitivity and promotes glucose and lipid metabolism, indirectly reducing the risk of atherosclerosis and supporting long-term blood pressure control." (PMID 41451127, 2025). "Understanding these interactions is essential for developing targeted interventions to mitigate the risk of atherosclerosis in insulin-resistant individuals." (PMID 40564010, 2025). "In both obese and non-obese mouse models, IGFBP-1 overexpression was associated with reduced blood pressure, improved insulin sensitivity, enhanced vasodilation, increased endothelial nitric oxide production, and protection against atherosclerosis." (PMID 40710778, 2025). "IR is characterized by reduced sensitivity to insulin's physiological effects, which is a crucial risk element for atherosclerosis." (PMID 40066350, 2025). "MiR-155 expression deficiency is characterized by the preservation of normal insulin sensitivity and a low risk of atherosclerosis." (PMID 40943138, 2025). "The interaction between FFAs, adhesion molecules, and impaired insulin signaling accelerates atherosclerosis and increases the risk of thrombotic complications." (PMID 40429748, 2025). "In fact, the authors showed that prepubertal glucose and insulin metabolism were associated with abnormal markers of atherosclerosis and early cardiovascular risk." (PMID 38920551, 2024). "Here, we show that IR haploinsufficient mice deficient in Apolipoprotein have accelerated atherosclerosis in the presence of normal glucose and insulin tolerance tests." (PMID 39401163, 2024). "Impaired insulin sensitivity is regarded as a key factor in the development of disorders linked to atherosclerosis, such as oxidative stress, endothelial dysfunction, inflammation, metabolic abnormalities, and hypertension." (PMID 38200157, 2024). "Our results supporting the concept of a beneficial effect of insulin on vascular SMCs in vivo are in accordance with recent reports in atherosclerosis models, where the vascular SMC deficiency of IRs accelerated atherosclerosis." (PMID 39195275, 2024). "Metabolic changes lead to elevated levels of circulating lipids, glucose, and insulin, which contribute to atherosclerosis and increase the risk of CVD." (PMID 39411175, 2024). "Ceramides are implicated in dysregulating insulin signalling, vascular endothelial function, inflammation, oxidative stress, and lipoprotein aggregation, thereby promoting atherosclerosis and vascular disease." (PMID 39408263, 2024). "Weight loss through dietary changes and increased physical activity can improve insulin sensitivity, reduce liver fat, and mitigate the risk of atherosclerosis." (PMID 38021670, 2023). "The mechanisms through which unfavorable lipid profiles increase risk from atherosclerosis and insulin dysregulation through excess lipid accumulation in the liver are complex but well established." (PMID 36872307, 2023). "The pathogenic mechanisms linking insulin resistance to atherosclerosis include proinflammatory state, perturbation of insulin signaling at the level of the intimal cells, and induction of other metabolic conditions." (PMID 38093371, 2023). "A low-carbohydrate, high-fat (LCHF) diet can reduce glucose and insulin spikes, improve insulin sensitivity, and lessen atherosclerosis risk factors." (PMID 37626767, 2023). "Gradual and sustainable weight loss strategies are recommended to reduce liver fat, improve insulin sensitivity, and lower the risk of atherosclerosis-related events." (PMID 38021670, 2023). "This protective effect of the Mediterranean diet has been attributed to its impact on insulin sensitivity, blood pressure, lipid profile, oxidative stress, and inflammatory biomarkers associated with atherosclerosis." (PMID 37630715, 2023).